CDC42 (cell division cycle 42)
Diseases named in the same sentence as CDC42 in open-access papers (continued):
Sharing a sentence is not in itself a finding about the gene and the disease.
cancer (continued). "In addition, PAK1 is a key downstream effector of Small Rho GTPases Rac1 and CDC42 and which was related to cell morphogenesis, motility, mitosis, survival, and angiogenesis in various cancers." (PMID 36675278, 2023). "HGF-related actin rearrangement, which is linked to cancer cell morphogenesis and metastasis, is primarily regulated by small GTPase activity, especially RhoA, Rac1, and Cdc42; however, various types of cancer cells use distinct signaling pathways in response to HGF to activate small GTPase." (PMID 35630066, 2022). "In addition, RAC1 and CDC42 are correlated with cancer metastasis, upregulating the PI3K signaling pathway to promote the migration and invasion of various types of cancer, including HCC." (PMID 36348464, 2022). "The Rac/Cdc42 downstream effector group I PAKs (PAKs 1–3) are direct downstream effectors of Rac and Cdc42 that have been the subject of intense investigation for targeted anticancer drugs due to their central role in cancer progression to metastasis." (PMID 36861094, 2022). "For vinorelbine, EPHA2 codes for EPH receptor A2, a tyrosine kinase involved in cancer-related signaling, while NGEF codes for a guanine nucleotide exchange factor associated with signaling from EPH receptor A2, RhoA, Rac1 and CDC42 as well as cellular transformation and tumorigenesis." (PMID 36139690, 2022). "Cdc42 is not mutated in cancers; instead, dysregulation of Cdc42 functions contribute to carcinogenesis." (PMID 36253497, 2022). "The central role of Rac and Cdc42 in multiple human cancers has been reviewed extensively." (PMID 36861094, 2022). "Apoptosis-related proteins expressed in ovaries (such as MAPK and Cdc42) may protect them from cancer." (PMID 35205296, 2022). "Notably, our test case—the CDC42/PAK1 complex—ishighly relevant for cancer drug discovery, being involved in cancercell invasion and metastasis." (PMID 35679463, 2022). "We have explored the subversion of Cdc42 regulated signalling in cancer in a recent review." (PMID 34100887, 2021). "We find that the Golgi apparatus pathways predominate over the Rac1/Cdc42 signaling pathways in controlling the cancer cell polarization, in contrast to the polarization of healthy tissues and cells that are primarily controlled by the Rac1/Cdc42 signaling pathways." (PMID 33499191, 2021). "In contrast to other reports in cancer cells, the reports suggested that, under most circumstances, these natural products significantly attenuated cell migration and invasion, perhaps via the Rho GTPases Rac and Cdc42." (PMID 34828017, 2021). "R-ketorolac may hold promise for future clinical use in cancers with elevated Rac1 and/or Cdc42 expression or activity." (PMID 33413202, 2021). "Relatively few Cdc42 mutations have been reported in cancer and there have been no recurring driver ­mutations identified in the gene." (PMID 34196668, 2021). "In addition to its function in normal cell activities, the abnormal high expression of Cdc42 in a variety of malignant tumors has been closely related to the occurrence, development, invasion and metastasis of malignant tumors." (PMID 33726765, 2021). "Rho-family GTPases have Cdc42, Rac1, and RhoA as the main subfamily and play important roles in various cell functions including angiogenesis and invasion, cytoskeletal structure formation, cell proliferation, apoptosis, and cancer metastasis." (PMID 34201921, 2021). "Additionally, the growing understanding of the role of the stroma in metastasis implicates Cdc42, with the Cdc42 GAP, ARHGAP31, being highly expressed in cancer-associated stroma." (PMID 34196668, 2021). "The dependence of such bridges on mTOR and CDC42 makes them amenable to small molecule intervention, providing additional therapeutic strategies to modulate senescent cell behaviour in both age-related diseases and cancer." (PMID 34373767, 2021).
cancer (continued). "Targeting Rho family-controlled signalling pathways is an approach that has recently enjoyed increased attention within the cancer therapeutics field, with strategies to target Cdc42 also having potential applications in neurodegeneration and infectious diseases." (PMID 34100887, 2021). "However, tumour suppressor-like activity of CDC42 has also been reported in human cancer, as well as mouse models." (PMID 34374417, 2021). "Intriguingly, both RAC1 activity and CDC42 activity have been associated with therapeutic resistance in different cancer types, including enzalutamide resistance in CRPC, and RAC/CDC42 inhibition has been suggested as a potential approach to overcome resistance to PI3K–AKT–mTOR-targeted treatments." (PMID 33105713, 2020). "Overexpression of Cdc42 GTPase was found in LSIL and HSIL and might be associated with progression of cervical lesion to cancer." (PMID 32443784, 2020). "Current studies on targeting Rac and Cdc42 have identified compounds that are poised to emerge as leading antimetastatic drugs for combination therapy with cytotoxic cancer therapies and to overcome resistance to current therapies targeting RTKs and PI3-K/Akt/mTOR signaling." (PMID 32322580, 2020). "Therefore, upregulated Rac and Cdc42 can drive malignant signaling during acquisition of resistance to cancer therapies targeting cell surface receptors, by acting downstream of therapy resistance mechanisms such as Ras/MAPK and PI3-K/mTOR signaling." (PMID 32322580, 2020). "In addition, Rac/Cdc42 inhibition has the potential to sensitize cancers to current chemotherapies such as taxanes and anthracyclines." (PMID 32322580, 2020). "Similarly, the effect of anti-cancer phytochemical rocaglamide-A inhibited the activity of RhoA, Rac1, and Cdc42 GTPases and suppressed metastasis formation." (PMID 32443784, 2020). "Disruption of the intra- and extracellular interactions of the VEGF/NRP1 axis or Cdc42 relocation could be performed in clinical practice because it might inhibit cancer cell motility and metastasis." (PMID 32139668, 2020). "It is known that the cytoskeleton remodelling and the acquisition of invasive phenotypes in cancer cells are orchestrated by members of the Rho-GTPase family, particularly, Cdc42 that has an important role in cancer cell invasion, acquisition of a mesenchymal phenotype, and formation of invadopodia." (PMID 32825056, 2020). "Even though oncogenic point mutations and splice variants have been reported from a number of cancers, Rac and Cdc42 do not have to be mutated in cancer to drive cancer progression." (PMID 32322580, 2020). "Furthermore, overexpression of Cdc42 has been reported to be in several human cancers, such as breast, non-small cell lung cancer, and melanoma." (PMID 32802134, 2020). "However, given that current natural compounds have the Rac and Cdc42 regulatory effects on cancer cell line, the specific mechanisms and therapeutic effects on osteoclastognesis remain incompletely understood." (PMID 32578854, 2020). "The expression of the Rho GTPases RAC1, RHOA, and CDC42 is also altered in several cancer types." (PMID 32526908, 2020). "Therefore, even though all Rho family GTPases play a role in cancer malignancy, this review will focus on new strategies to target Rac and Cdc42 activation via blocking the exchange of GDP to GTP." (PMID 32322580, 2020). "Rac1 and Cdc42 are unique in that they act as molecular switches that do not have to be mutated to drive cancer progression but are activated by oncogenic cell surface receptors." (PMID 32322580, 2020). "Therefore, an additional benefit of Rac/Cdc42 inhibition is the reduction in bone marrow-derived cells that promote the metastatic dissemination of cancer cells in the TMEM." (PMID 32322580, 2020). "CDC42 is crucial for EGF- stimulated migration in MTLn3 carcinoma cells." (PMID 32733636, 2020).
cancer (continued). "We also discuss how simultaneous inhibition of these two distinct classes of targets, COX enzymes and Rac1/Cdc42, by S-ketorolac and R-ketorolac respectively, could each contribute to anti-cancer activity." (PMID 31344967, 2019). "It is suggested that Cdc42 participates in anti-cancer drug resistance by interacting with N-WASP and Arp2/3 to promote actin polymerization, microfilament cytoskeleton rearrangement, intracellular material flow acceleration and promotion of intracellular drug excretion to the extracellular space." (PMID 30754684, 2019). "Additionally, some double Rac/Cdc42 inhibitors have been developed due to the similar roles these two small GTPases perform in cancer promotion and progression." (PMID 30884855, 2019). "Cdc42 not only participates in cancer cell growth but also survival under particular circumstances." (PMID 30621321, 2019). "The fact that stiffness-mediated dormancy was observed in vivo suggests that nuclear Cdc42 activity might also be relevant in cancer." (PMID 31380367, 2019). "Additionally, accumulating evidences showed that Cdc42 plays a crucial role as metastasis regulator in human cancer models." (PMID 31817718, 2019). "Future work is needed to test how essential Cdc42 is for this process and whether identifying drugs that inhibit nuclear translocation of Cdc42 might be useful for cancer therapeutics." (PMID 31380367, 2019). "The abnormal activation of CDC42 may alter the various downstream signaling pathways regulated by CDC42, leading to uncontrolled cell proliferation and cancer development." (PMID 30717410, 2019). "Many studies have indicated that Cdc42 mRNA is a direct target of miR-29a in cancer progression." (PMID 31662747, 2019). "Additionally, a recent study showed that gonadotropin-releasing hormone regulates p120ctn cytoplasmic translocation to promote cancer cell migration and invasion via Rac1 and Cdc42." (PMID 30795761, 2019). "A previous report mentioned that CDC42 has a cancer promoting role under the control of Ras signaling pathway and also CDC42 binds to p85 regulatory subunit of PI3K to active the downstream Akt signaling pathway, which are highly activated during cancer cell proliferation." (PMID 30717410, 2019). "Furthermore, CDC42 is highly expressed and serves as an oncogene in many cancers, such as nasopharyngeal carcinoma, gastric cancer and glioma." (PMID 31889909, 2019). "Another potential inhibitor of Cdc42 with therapeutic applications in cancer is ZCL278, a 4-bromine-2-chlorophenol derivative that disrupts the joining between Cdc42 and intersectin (ITSN), which is a Cdc42-specific GEF enzyme, leading to inhibiting the activation of this small GTPase." (PMID 30884855, 2019). "Its overexpression in cancer cells is induced by Cdc42 through EGFR signaling." (PMID 30754684, 2019). "CDC42 is a small GTPase involved in tumor initiation and cancer progression." (PMID 30717410, 2019). "Moreover, recent studies show that in most human cancers Cdc42 is abnormally expressed and promoting neoplastic growth and metastasis." (PMID 29596304, 2018). "Blocking the formation of the MISP/IQGAP1/Cdc42 complex might have therapeutic potential for specific cancer types." (PMID 29679050, 2018). "Our findings suggest that combining high-affinity peptide-binding sequences with short electrostatic steering sequences could increase the efficacy of peptidomimetic candidates designed to interfere with Cdc42 signaling in cancer." (PMID 30104412, 2018). "Furthermore, morphological change and migration inhibition of cancer cells were accompanied by EMT repression, Golgi reorientation, and polarity disruption caused by alteration of cdc42 activity via a decrease in Rho-GAP, ARHGAP21." (PMID 30504808, 2018). "Many studies have reported that Cdc42 is regulated by various microRNAs in cancer." (PMID 29596304, 2018). "In conclusion, the role of Cdc42 in cancer is diverse and needs further exploration." (PMID 29596304, 2018).
cancer (continued). "Targeting either the MISP/IQGAP1 or the Cdc42/IQGAP1 interaction may decrease the amount of active Cdc42 in cancer cells and thereby prevent tumor progression." (PMID 29679050, 2018). "There is ample evidence to suggest that Cdc42 is an attractive therapeutic target in cancers." (PMID 29596304, 2018). "The gene expression of Cdc42 is different in several types of cancer." (PMID 29596304, 2018). "Finally, cell division control protein 42 homolog (CDC42)-mediated β1 integrin expression also facilitates cancer cell interaction with endothelial cells and transendothelial migration." (PMID 28665313, 2017). "CDC42 is known to contribute to tumorigenesis and cancer progression." (PMID 28282856, 2017). "Cdc42 is known to regulate cell-matrix contacts through β1-integrin in certain cancer cells, so it is plausible to hypothesise that its depletion may weaken focal adhesions, or impair integrin signalling, to mimic detachment and so induce entosis." (PMID 28693721, 2017). "However, the role of CDC42 in global gene transcriptional regulation in cancer remains poorly understood." (PMID 28460460, 2017). "Although there are no known activating mutations of CDC42, which result in its proto-oncogenic behavior, it is reported to be overexpressed in several different cancers." (PMID 28282856, 2017). "Cdc42 stimulates filopodia formation, RhoA induces the formation of stress fibers, and Rac1 induces lamellipodia formation, all of which play critical roles in cancer cell invasion and metastasis." (PMID 28423650, 2017). "Therefore, since Cdc42 pathway is mediated by Src kinase, there is a link between cancer and filopodia formation (Cancer – Src kinase – Cdc42 – Filopodia)." (PMID 27014223, 2016). "Cdc42 and JNK are closely associated with cancer cell metastasis." (PMID 27367023, 2016). "Thus, suppressing HDAC6 or MEK/ROCK together promotes normal epithelial organization in HER2-positive BT474 cancer cells that have low Cdc42 function." (PMID 26783207, 2016). "It is currently unknown whether cdc42 has a contribution to miR-204-mediated dual function in cancer cells." (PMID 27438705, 2016). "Besides XRN1, cdc42 is another miR-204 target which has a dual yet opposite growth-regulatory function in cancer cells." (PMID 27438705, 2016). "Together, our results demonstrate that Mig-6 inhibition of Cdc42 signaling is critical in Mig-6 function to suppress cell migration and that dysregulation of this pathway may play a critical role in cancer development." (PMID 27341132, 2016). "Likewise, HER2+-specific circRNAs (n = 245), annotated with over 1,500 protein-coding genes, had 855 cancer-related genes (p-value = 1.65E-14–2.24E-03) involved in Wnt signaling, Cdc42, and ILK signaling pathways." (PMID 27829232, 2016). "Ubiquitylation of Rac1, RhoA and Cdc42 can be deregulated in cancer cell lines, a fact that could indicate a link between Rho GTPase protein ubiquitylation and cancer." (PMID 27104658, 2016). "This study indicates that, in addition to direct inhibition of EGFR, Mig-6 can function to inhibit Cdc42, and that dysregulation of Cdc42 pathway may play an important role in cancer metastasis." (PMID 27341132, 2016). "Although the importance of Rac1/Cdc42 activation is well documented in cancer aggressiveness, the clinical importance of GIT1 remains largely unknown." (PMID 26462147, 2015). "Reported targets of miR-330-3p in various cancer types include Sp1, CDC42 and E2F1." (PMID 26221725, 2015). "Accumulating evidence indicates that CDC42 has an important but complex role in cancer." (PMID 26336992, 2015). "Increased CDC42 expression has been observed in multiple human cancers, including CRC, and elevated CDC42 may also contribute to cancer therapy resistance." (PMID 25379703, 2014).
cancer (continued). "In response to extracellular ligand binding, integrins undergo a conformational change that permits the recruitment of cytoplasmic adaptor proteins and signaling molecules, including small Rho GTPases, Cdc42, Rac1 and RhoA, which are key players in cell migration and cancer metastasis." (PMID 25149533, 2014). "Thus, inhibition of CDC42 expression is likely to be a key mechanism by which miR-18a impairs cancer cell growth." (PMID 25379703, 2014). "Our data in SW620 cells suggest that AZA197 may impact cancer cell viability at concentrations that inhibit Cdc42, cell proliferation and actin cytoskeletal changes in SW620 cells." (PMID 24279335, 2013). "Although further investigations may be needed to examine the underlying mechanisms by which NO controls Cdc42 and filopodia formation, this study first revealed the novel effect NO has on cancer cell migration through a Cdc42-dependent mechanism." (PMID 23984323, 2013). "Cdc42 has mostly been studied as a regulator of the actin cytoskeleton and for its role in generating actin-rich protrusions (called invadopodia) and, in cancer biology, as facilitating cancer cell migration and metastasis." (PMID 23606532, 2013). "Another group of differentially expressed proteins are associated with increased cancer cell motility and invasiveness, which include EphA2, BCAS1, S100 protein family members, Rho family members, Ral-A, Rab family members, Cdc42, MARCKS, Ezrin, Galectins 1 and 3 among others." (PMID 22417809, 2012). "While mutations in Cdc42 have not been reported in human cancer, upregulation of Cdc42 protein expression or activity has been reported in a variety of tumor types and in some instances have been correlated with poor prognosis." (PMID 22719838, 2012). "Its binding to Cdc42 is important for establishing cell polarity, and one possibility is that Pak4 may interfere with the Cdc42:Par6 interaction when it is overexpressed, thereby disrupting cell polarity in cancer." (PMID 23326684, 2012). "The effects of bacteria on cell signalling including Ras and Cdc42, MT1-MMP and invadopodia (detailed in step 2) associated with membrane ruffles and uptake of bacteria; incredibly similar pathways are detailed as associated with cancer invasion into the bloodstream and metastases." (PMID 38535967, 2024). "Therefore, we investigated the evolutionary history of cancer associated gene sequences across 384 mammalian taxa, to detect signatures of selection across categories of oncogenes (GRB2, FGL2 and CDC42), tumour suppressors (LITAF, Casp8 and BRCA2) and immune genes (IL2, CD274 and B2M)." (PMID 38773187, 2024). "In addition, the biological activity of particular pathways downstream of NRBP1 may be context-dependent, as exemplified by Cdc42 exhibiting oncogenic or tumour suppressor functions depending on cancer type." (PMID 36693952, 2023). "The crosstalk between the Cdc42 molecule and the network of effectors in the immune system is increasingly recognized, and new therapeutic targets based on new regulator partners are expected, and their translation into the treatment strategies for cancer creating a future therapeutic perspective." (PMID 37347054, 2023). "Therefore, we tested the hypothesis that Rac and Cdc42 inhibitors target immunosuppressive immune cells, in addition to cancer cells." (PMID 37397366, 2023). "The dysregulation of Cdc42 mediated Gene33 pathway may play a critical role in cancer development." (PMID 35186026, 2022). "Additionally, it is known that testosterone triggers the activation of Cdc42 in cancer cells." (PMID 34200797, 2021). "Thus, low levels of RhoH resulting from aSHM might directly or indirectly promote Rac1-, RhoA- or Cdc42-induced cell division and migration, leading to an increase in cancer progression." (PMID 33923951, 2021).